AURKAP1 (aurora kinase A pseudogene 1)
Synonyms: AurAps1; formerly STK6P; AURKAPS1
Gene: Transcribed processed pseudogene on chromosome 1 (220,266,706 to 220,267,917, reverse strand). Ensembl gene ENSG00000213033.
Diseases named in the same sentence as AURKAP1 in open-access papers:
AURKAP1 is named in the same sentence as 5 diseases in open-access papers, as found by Europe PMC text mining. Sharing a sentence is not in itself a finding about the gene and the disease.
AURKAP1 shares sentences with these, for which no sentence is quoted: cancer (2 papers); Hepatitis (1); hepatocellular carcinoma (1); liver cancer (1); tumor (1).